CHIT1 (chitinase 1)
Diseases named in the same sentence as CHIT1 in open-access papers (continued):
Sharing a sentence is not in itself a finding about the gene and the disease.
malaria (3 papers, 2007 to 2021). Malaria is a serious and sometimes fatal disease caused by a parasite that commonly infects a certain type of mosquito which feeds on humans. "Therefore, the catalytically inactive form of human CHIT1 has been suggested to reduce malaria transmission at subsequent bites, thus high frequencies of the duplication may confer some level of protection against malaria at the community level." (PMID 25256524, 2014).
autoimmune disease (2 papers, 2021 to 2024). A disorder resulting from loss of function or tissue destruction of an organ or multiple organs, arising from humoral or cellular immune responses of the individual to their own tissue constituents. "Others were associated with autoimmune disease, such as systemic lupus erythematosus (SLE), ALS, and RA: CHIT1, IL18RAP, PHF24, and TPST1." (PMID 38978787, 2024).
cognitive deficits (2 papers, 2023 to 2025). "Chitinase 1 (CHIT1) ameliorated cognitive deficits and neuroinflammation via HDAC3 inhibition." (PMID 40814109, 2025). "They demonstrated that CHIT-1 promotes brain inflammation via the HDAC3/NF-κB p65 pathway, contributing to improvement of cognitive impairment and AD progression." (PMID 37047273, 2023).
colorectal cancer (2 papers, 2016 to 2021). A primary or metastatic malignant neoplasm that affects the colon or rectum. "In this study, we investigated the associations between CHIT1 gene variants (rs61745299 and rs35920428) and the risk of colorectal cancer in the Chinese Han population." (PMID 27153562, 2016).
COVID-19 (2 papers, 2021 to 2025). A disease caused by infection with severe acute respiratory syndrome coronavirus 2. "On March 24, 2020, Unco Arendy Therapeutics announced that it is studying OATD-01, a CHIT1 inhibitor, to help treat pulmonary fibrosis in COVID-19 patients." (PMID 35069217, 2021). "Studies are currently underway to determine whether patients who have died from COVID-19 have increased CHIT1 expression in their lung tissues, which may lead to a positive effect of OATD-01 on the pulmonary fibrotic development of the disease." (PMID 35069217, 2021).
diabetic nephropathy (2 papers, 2015 to 2017). "We recently demonstrated that increased plasma CHIT1 and YKL-40 are associated with diabetic nephropathy and may participate in the progression of vascular damage within glomeruli in diabetic patients." (PMID 26517273, 2015).
fibrosis (2 papers, 2022). the formation of excess fibrous connective tissue in an organ or tissue in a reparative or reactive process. "Among these genes, the expression of inflammation-associated FCER1G, OSM, VEGFA, and ZAP70 was lower in high-grade fibrosis than in low-grade fibrosis, whereas CHIT1 expression, which is associated with fibrogenic activity of macrophages, was higher in high-grade fibrosis." (PMID 35052861, 2022). "In this study, we also demonstrated the upregulation of pro-inflammatory genes in F1/F2 fibrosis and subsequent decrease in the expression of these genes in F3/F4 fibrosis; however, the profibrogenic CHIT1 gene was upregulated in the advanced fibrosis stages." (PMID 35052861, 2022).
filariasis (2 papers, 2007 to 2019). "This does not correlate with a previous study that linked the mutant CHIT1 genotype to filariasis susceptibility." (PMID 17765019, 2007).
frontotemporal dementia (2 papers, 2020 to 2021). Frontotemporal dementia (FTD) comprises a group of neurodegenerative disorders, characterized by progressive changes in behavior, executive dysfunction and language impairment, as a result of degeneration of the medial prefrontal and frontoinsular cortices. "However, because of overlapping levels of CHIT1 in prion disease, AD and frontotemporal lobar degeneration (FTLD), it is of limited diagnostic value." (PMID 34321067, 2021).
hookworm infection (2 papers, 2007 to 2014). "We conclude that the CHIT1 genotype does not play a crucial role in protection against hookworm infection." (PMID 17765019, 2007).
metabolic dysfunction-associated steatohepatitis (2 papers, 2020 to 2025). Metabolic dysfunction-associated steatohepatitis (MASH, formerly known as nonalcoholic steatohepatitis or NASH) is a type of fatty liver disease. "In this study, we investigated the efficacy of CHIT1 inhibitor (OATD-01) in three different animal models of metabolic dysfunction-associated steatohepatitis (MASH)." (PMID 40510344, 2025). "CHIT1, predominantly secreted by macrophages, is overexpressed in metabolic dysfunction-associated steatohepatitis (MASH)." (PMID 40510344, 2025). "Human Kupffer cells were also implemented to investigate the role of CHIT1 in nonalcoholic steatohepatitis." (PMID 32655419, 2020).
pulmonary sarcoidosis (2 papers, 2025). Sarcoidosis affecting the lung parenchyma. "CHIT1 has been recently described as a biomarker of disease activity and severity in pulmonary sarcoidosis." (PMID 40928208, 2025).
systemic candidiasis (2 papers, 2021 to 2025). "Taken together, these data indicate the loss of Chit1 is beneficial in mounting an efficient systemic response against systemic candidiasis in a mouse model." (PMID 33796101, 2021). "In this study, we used mice genetically deficient in Chit1 to determine its necessity against systemic candidiasis." (PMID 33796101, 2021). "In the current study, using knockout mice, we determined the role of Chit1 against systemic candidiasis." (PMID 33796101, 2021). "We show the release of the anti-candidal enzyme chitotriosidase (Chit1) can negatively affect the immune response against systemic candidiasis." (PMID 33796101, 2021). "For instance, we found that plasma levels of Chit1 is parallel with the extent of systemic candidiasis in experimental animals used throughout this study." (PMID 33796101, 2021). "However, we show that Chit1 is not an essential component of the inflammatory response to systemic candidiasis." (PMID 33796101, 2021).
acute coronary syndrome (1 paper, 2025). Signs and symptoms related to acute ischemia of the myocardium secondary to coronary artery disease. "In acute coronary syndrome, an association was found between plasma CHIT1 activity and the inflammatory response." (PMID 41303283, 2025).
allergic asthma (1 paper, 2025). A asthma with a basis in a pathological type I hypersensitivity reaction. "Our results support the notion that CHIT1 enzymatic activity may be an advantageous target for intervention in HDM–chitin–TLR2-mediated pathologies such as allergic asthma or the skin condition rosacea." (PMID 40098951, 2025).
allergies (1 paper, 2025). "Aside from the detection of pathogenic fungi, our data indicate that the link between CHIT1 and the TLR2 sensing system may also be relevant in the context of HDM allergies, where CHIT1-generated chitin oligomers could serve as TLR2-acting adjuvants for HDM antigens." (PMID 40098951, 2025).
bronchiectasis (1 paper, 2022). Segmental, irreversible dilation of the bronchial tree resulting in the accumulation of secretions which leads to obstruction. "The study of human chitinase activity, chitotriosidase (CHIT1) and acidic mammalian chitinase (AMC), established in CF, has, however, been evaluated in bronchiectasis and demonstrates a key association with individuals who frequently exacerbate in South-East Asian settings." (PMID 35628736, 2022).
chronic asthma (1 paper, 2023). An asthma that is characterized by the development of persistent airway inflammation and recurrent attacks of breathlessness and wheezing, which vary in severity and frequency. "OATD-01, a chitinase inhibitor, was tested in a 7-week-long house dust mite (HDM) murine model of chronic asthma characterized by accumulation of CHIT1-expressing macrophages." (PMID 36902148, 2023).
chronic lung disease (1 paper, 2023). According to the definitions of the American and British Thoracic Societies, including pulmonary functional tests, X-rays, and CT scans for items such as fibrosis, bronchiectasis, bullae, emphysema, nodular or lymphomatous abnormalities. "Pharmacological inhibition for CHIT1 can be a treatment of various chronic lung diseases with ongoing tissue remodeling processes." (PMID 36902148, 2023).
coccidioidomycosis (1 paper, 2022). A fungal infection caused by Coccidioides immitis. "Here, we demonstrate that a hybridoma-generated mouse mAb against chitinase 1 (CTS1), an antigen from Coccidioides spp., can be biologically engineered for use with serologic diagnostic test kits for coccidioidomycosis (Valley Fever) using plant expression." (PMID 36119630, 2022).
colonic inflammation (1 paper, 2022). "It has been found that CHIT1 was down-regulated in active UC patients, while in healthy controls it was actively secreted by mucin-producing cells, and it has been postulated that decreased secretion of this enzyme exacerbates colonic inflammation." (PMID 35216274, 2022). "Also, given the apparent role of CHIT-1 in colon inflammation, selective CHIT-1 inhibition or simultaneous inhibition of both chitinases may provide efficient strategies for treatment of colitis." (PMID 35216274, 2022). "Consequently, inhibition of chitinases AMCase and CHIT1, and also of the chitinase-like protein YKL-40 (CHI3L1), may prove a viable strategy for treatment of inflammatory and fibrotic diseases, including colitis." (PMID 35216274, 2022).
eumycetoma (1 paper, 2020). "Though both CHIA and CHIT1 were expressed in mycetoma lesions, a 24-bp insertion in CHIT1 resulting in impaired enzyme activity was found to be significantly associated with eumycetoma." (PMID 32352976, 2020).
Fusarium infection (1 paper, 2009). "We also observed defense related genes like chitinase 1 and PR10, and secondary metabolism genes like chalcone synthase and isoflavone 3'-hydroxylase to be repressed during Fusarium infection." (PMID 19732460, 2009).
kidney damage (1 paper, 2025). "In AKI, inflammation, immune cell infiltration and oxidative stress are significant contributors to kidney damage, and elevated CHIT1 levels could be linked to the inflammatory response in this context." (PMID 41303283, 2025).
leprosy (1 paper, 2020). Leprosy is a chronic infectious disease affecting primarily the skin and peripheral nervous system. "The other, meanwhile, was observed primarily in a single leprosy patient and was defined by genes involved in extracellular proteolysis (LYZ, CHIT1, and CHI3L1)." (PMID 33053333, 2020).
lung carcinoma (1 paper, 2022). "CHT, also called Chitinase 1, is encoded by the CHIT1 gene, and its increased enzymatic activity was previously associated with lung cancer." (PMID 36101414, 2022). "CHIT1, mainly produced by activating macrophages, both in normal and inflammatory conditions, could represent a promising biomarker correlated with disease activity, severity, and extent in patients with several pulmonary infections and diseases with an inflammatory component, including lung cancer." (PMID 36101414, 2022).
lymphoma (1 paper, 2022). A malignant (clonal) proliferation of B- lymphocytes or T- lymphocytes which involves the lymph nodes, bone marrow and/or extranodal sites. "However, CHIT1 also showed differences in lymphoma patients with different immune status, affected the prognosis of lymphoma patients, and was associated with the infiltration of immune cells." (PMID 36249005, 2022). "In further studies, we will further study the effect of CHIT1 on lymphoma with different immune status." (PMID 36249005, 2022). "Two deaths of EBV+ patients were observed in lymphoma patients included in the study, and in their PCR results we found that the CHIT1 gene in both patients had the significantly lowest expression in all samples." (PMID 36249005, 2022). "We reported that down-regulation of CHIT1, SIGLEC15, PLA2G2D and TMEM163 was associated with poor prognosis in immunocompetent NHL, and expression levels of four genes were lower in lymphoma than in normal tissues." (PMID 36249005, 2022). "Four differential genes between EBV+ and EBV- lymphoma patients were screened out with the significance of the survival and prognosis of lymphoma, including CHIT1, SIGLEC15, PLA2G2D and TMEM163." (PMID 36249005, 2022). "Therefore, the low expression of CHIT1 in EBV+ lymphoma patients was closely related to the poor prognosis and even death of patients." (PMID 36249005, 2022). "The role of M0, M2 macrophages in tumor immune microenvironment is consistent with the favorable genes of CHIT1, SIGLEC15, PLA2G2D and TMEM163 for the prognosis of lymphoma patients." (PMID 36249005, 2022). "CHIT1 and TMEM163 have been identified using RT-qPCR and are able to function as potential novel therapeutic targets for EBV+ lymphoma patients." (PMID 36249005, 2022). "Our data suggest that differences in expression levels of CHIT1 and TMEM163 and macrophage infiltration levels may be important drivers of poor prognosis of EBV+ lymphoma patients." (PMID 36249005, 2022).
MELAS syndrome (1 paper, 2025). MELAS (Mitochondrial myopathy, encephalopathy, lactic acidosis, and stroke) syndrome is a rare progressive multisystemic disorder characterized by encephalomyopathy, lactic acidosis, and stroke-like episodes. "However, there was a tendency for higher CHIT1 concentrations in patients with central nervous system involvement (MELAS syndrome), while FGF21 and GDF15 were not relevantly altered in these patients." (PMID 39891741, 2025).
motor neuron degeneration (1 paper, 2019). "Based on these results, we speculate that the differences in NfL and p-tau/t-tau values might not be influenced by the presence of ALS pathology, while the distribution of CHIT1 levels appears to be influenced by both the motor neuron degeneration and the type of proteinopathy." (PMID 31892365, 2019).
nematode infections (1 paper, 2012). "Although both AMCase and CHIT1 are upregulated in certain bacterial and nematode infections only AMCase was significantly increased in the brain following Toxoplasma infection." (PMID 23209401, 2012).
neuromyelitis optica (1 paper, 2019). A rare inflammatory disease of the central nervous system characterized mainly by attacks of uni- or bilateral optic neuritis (ON) and acute myelitis. "Similar to murine Chi3l3 and Chi3l1, their human paralogues CHI3L1 and CHIT1 are highly abundant in the CNS during acute demyelinating diseases, including relapsing-remitting MS (RRMS) and neuromyelitis optica, but not chronic MS37." (PMID 30644388, 2019).
obstructive sleep apnea (1 paper, 2018). "The aim of this preliminary observational study was to assess the roles and interaction of obstructive sleep apnea (OSA) severity and body mass index (BMI) with plasma CHI3L1 levels and CHIT1 activity in patients with moderate to severe OSA." (PMID 30311184, 2018).
parasite (1 paper, 2020). "However, the regulation and role of CHIT1 in bryozoans to parasite infection is not known." (PMID 32824626, 2020).
prion disease (1 paper, 2019). A transmissible disease that is caused by a protein that is able to induce abnormal folding of normal cellular proteins, leading to characteristic spongiform brain changes, which are associated with neuronal loss without an inflammatory response. "In each diagnostic category, the frequency of CHIT1 genotypes fit the Hardy-Weinberg equilibrium (prion disease: p = 0.735; AD: p = 0.909; FTD: p = 0.429; controls: p = 0.541)." (PMID 31892365, 2019). "In the prion disease group, the disease stage correlated with CHIT1 (Spearman’s rho = 0.287; p = 0.009), YKL-40 (Spearman’s rho = 0.366, p = 0.001), and t-tau (Spearman’s rho = 0.354, p = 0.001) values." (PMID 31892365, 2019). "In this study, we measured the CSF levels of the glial markers CHIT1, YKL-40 and GFAP and several other biomarkers of neurodegeneration, in AD, prion disease subtypes, and clinicopathological subgroups of FTD/FTLD." (PMID 31892365, 2019). "Our results demonstrate a significant and largely overlapping increase in the levels of CHIT1, YKL-40, and GFAP in prion disease, AD, and FTLD, thus supporting the idea of a shared CSF neuroinflammatory profile in neurodegenerative dementias." (PMID 31892365, 2019). "Each ND group showed increased levels of CHIT1, YKL-40, and GFAP compared to controls with a difference between prion disease and AD or FTLD limited to YKL-40, which showed higher values in the former group." (PMID 31892365, 2019). "CHIT1 levels were reduced in both heterozygotes and homozygotes for the CHIT1 24-bp duplication (rs3831317) in FTLD and controls, but this effect was less significant in AD and prion disease." (PMID 31892365, 2019). "Moreover, the results did not change after excluding the homozygotes for the CHIT1 24-bp duplication (prion disease vs. controls p < 0.001, AD vs. controls p = 0.046, FTD vs. controls p = 0.006)." (PMID 31892365, 2019). "In terms of diagnostic value, we confirmed that only YKL-40 demonstrates a moderate accuracy with ≥ 80% sensitivity and specificity in discriminating between controls and AD or prion disease, while neither YKL-40 nor CHIT1 or GFAP has a significant diagnostic value in any other comparison." (PMID 31892365, 2019). "Otherwise, the heterozygotes for the 24-bp duplication showed significantly reduced levels of CHIT1 in comparison with the non-carriers in both FTD and controls but not in prion disease and AD." (PMID 31892365, 2019). "Our finding of increased CSF CHIT1 and GFAP levels in prion disease, AD, and FTD compared to controls, but without significant differences between the three NDs, adds consistency to previous studies in smaller cohorts." (PMID 31892365, 2019).
pterygium (1 paper, 2025). A wedge-shaped fibrovascular lesion arising from the bulbar conjunctiva and extending to the cornea. "The CHIT1 gene, which plays a role in antifungal defenses, displayed the highest expression in five pterygium tissue samples compared to healthy conjunctiva controls, suggesting the potential involvement of Malassezia restricta in pterygium development." (PMID 40243577, 2025). "Several lines of evidence, including the highest expression of CHIT1, high prevalence of M2 macrophages, and elevated expression of IL33, suggest that this yeast could actively contribute to the development of pterygium rather than being a coincidental finding." (PMID 40243577, 2025).
pulmonary fungal infection (1 paper, 2015). "CD11b+ DC, and importantly recognition of chitin via Chit1, drive the generation of deleterious Th2 cells responding to pulmonary fungal infection." (PMID 25764512, 2015). "Furthermore, the varying pH-dependent enzymatic activity of Chit1 and AMCase suggest these enzymes may function in disparate anatomical and subcellular compartments that may bias their participation in response to pulmonary fungal infection." (PMID 25764512, 2015).
pulmonary tuberculosis (1 paper, 2023). A bacterial infection that affects the lungs and is caused by Mycobacterium tuberculosis. "The association between the severity of active pulmonary tuberculosis (APTB) and elevated serum levels of CHIT1 has been previously demonstrated in clinical studies." (PMID 38137331, 2023).
squamous carcinoma (1 paper, 2022). "The analysis of CHIT1 mean values according to cancer type indicated various concentration differences, with highest levels in squamous carcinoma, lower levels in the case of NSCLC (adenocarcinoma and the smallest recorded in SCLC." (PMID 36101414, 2022).
triple-negative breast carcinoma (1 paper, 2024). An invasive breast carcinoma which is negative for expression of estrogen receptor (ER), progesterone receptor (PR), and human epidermal growth factor receptor 2 (HER2). "Song and Shao (2024) have also proposed CHIT1 as 1 of 12 genes in an immune-mediated genetic prognostic risk score model when administering immunotherapy in triple negative breast cancer." (PMID 39201744, 2024).